PTPN22 (protein tyrosine phosphatase non-receptor type 22)
Diseases named in the same sentence as PTPN22 in open-access papers (continued):
Sharing a sentence is not in itself a finding about the gene and the disease.
lupus nephritis (5 papers, 2008 to 2025). Glomerulonephritis in the context of systemic lupus erythematosus. "In vivo loss of PTPN22 Ser449 phosphorylation reduced T cell responses and suppressed experimental lupus nephritis." (PMID 40911684, 2025). "For example, PDCD1 has been shown to be associated with lupus nephritis and anti-phospholipid antibodies in ethnic subgroups, and PTPN22 is primarily associated with anti-cyclic citrullinated peptide (anti-CCP) and rheumatoid factor (RF) autoantibody positive RA." (PMID 18516230, 2008). "Further studies suggested that downregulation of PTPN22 mRNA expression levels was associated with higher SLE activity and more severe lupus nephritis." (PMID 38352885, 2024). "PTPN22 and IL10 gene expression was negatively correlated with Mex-SLEDAI score and were notably downregulated in SLE patients with lupus nephritis." (PMID 36428917, 2022).
viral infection (5 papers, 2017 to 2025). "Taken together, our data show that the pro-autoimmune allele of Ptpn22 drives a beneficial anti-viral immune response thereby preventing what is normally a chronic virus infection." (PMID 38512979, 2024). "Recent studies addressing the role of Ptpn22 in antiviral immunity either by studying PTPN22−/− mice or cells from carriers of the autoimmune-associated variant showed a clear link between PTPN22 and effective responses to acute viral infection." (PMID 28747914, 2017). "The influence of PTPN22 in T cell exhaustion has been studied most extensively in the context of chronic viral infections." (PMID 33425916, 2020). "Together, these findings identify a CD8 T cell-extrinsic role for PTPN22 in weakening early CD8 T cell responses to collectively promote persistence of a chronic viral infection." (PMID 28747914, 2017). "Infection of PTPN22–/– and control mice with lymphocytic choriomeningitis virus (LCMV) clone 13 resulted in chronic infection of the host and PTPN22–/– mice controlled the viral infection more efficiently than control mice." (PMID 33425916, 2020).
ankylosing spondylitis (4 papers, 2010 to 2020). An autoimmune chronic inflammatory disorder characterized by inflammation in the vertebral joints of the spine and sacroiliac joints. "This study aimed to examine the predisposition of PTPN22 SNPs to Vogt-Koyanagi-Harada (VKH) syndrome and acute anterior uveitis (AAU) associated with ankylosing spondylitis (AS)." (PMID 24816862, 2014). "We now extend these studies on PTPN22 gene polymorphisms in two other frequently observed uveitis entities in China, namely VKH syndrome and anterior uveitis associated with ankylosing spondylitis." (PMID 24816862, 2014).
celiac disease (4 papers, 2011 to 2024). An autoimmune genetic disorder with an unknown pattern of inheritance that primarily affects the digestive tract. "Lastly, four of the nine TPOA associated SNPs (in SH2B3, CTLA4, BACH2 and UBASH3A) have also been associated with celiac disease (but not the SNPs in RASGRP1, STAT4, PTPN22, IL2 and FCRL3)." (PMID 21829393, 2011).
lymphopenia (4 papers, 2017 to 2024). Reduction in the number of lymphocytes. "In keeping with this, PTPN22-deficient or PTPN22 R619W mutant murine T cells adoptively transferred into immunodeficient lymphopenic hosts showed a higher lymphopenia-induced proliferation rate than WT cells." (PMID 32047502, 2020). "Because LCMV Cl13-infected mice experience severe lymphopenia caused by immunopathology, we analyzed T and B cell populations 8, 15, and 30 dpi in PTPN22+/+ and PTPN22−/− animals." (PMID 28747914, 2017). "As the PTPN22R620W variant is found in man rather than a full KO, we tested whether the equivalent mutation in mouse (R619W) behaved more similarly to either PTPN22 WT or KO cells in the context of lymphopenia." (PMID 32047502, 2020). "We induced lymphopenia by treating wild-type or PTPN22 knock-out mice with T cell depleting antibodies and monitored reconstitution of the T cell pool." (PMID 32047502, 2020). "Phenotypic analysis of the T cells showed increased frequency of CD44+ and significantly higher expression of Tbet and IFNγ in PTPN22 KO CD4 T cells after they underwent lymphopenia induced proliferation." (PMID 32047502, 2020). "Together these data show that proliferation induced by lymphopenia is intrinsically regulated by PTPN22 protein in both CD4 and CD8 T cells." (PMID 32047502, 2020). "Similarly, following induction of lymphopenia by antibody-mediated T cell depletion, reconstitution of the T cell pool was accelerated in Ptpn22-/- as compared to control mice." (PMID 39039893, 2024). "Based on our findings we conclude that antibody mediated T cell lymphopenia does not trigger overt auto-aggression in PTPN22 KO mice although PTPN22 deficient T cells showed a pronounced effector phenotype." (PMID 32047502, 2020). "T cell numbers were significantly higher in PTPN22 KO than in WT mice when IL-7 signaling was blocked indicating that the availability of IL-7 can mask dysregulated self-peptide MHC/TCR mediated proliferation during lymphopenia." (PMID 32047502, 2020). "PTPN22 is expressed in all hematopoietic cells and regulates production of cytokines which could affect peripheral T cell expansion in response to lymphopenia in the Ab depletion models we were analyzing." (PMID 32047502, 2020). "To test whether Ptpn22 regulated homeostatic T cell proliferation in response to transient lymphopenia in mice we chose an Ab-mediated lymphopenia model, as this was similar to the mode of action of drugs such as Alemtuzumab which is used for lymphodepletion therapy in man." (PMID 32047502, 2020). "However, IFNγ expression was significantly increased in PTPN22 KO CD4 T cells indicating that PTPN22 influences the inflammatory potential of T helper cells and the difference between WT and KO was particularly pronounced in T cells of mice that underwent lymphopenia induced proliferation." (PMID 32047502, 2020). "Additionally, considering the role of the PTPN22 gene product in T cell regulation, we evaluated the expression of PTPN22 mRNA according to lymphopenia status, this was not significant (6.01 ± 9.69 vs. 10.0 ± 16.6; p = 0.76)." (PMID 36428917, 2022). "Higher numbers of PTPN22 KO compared to WT CD4 T cells were recovered from lymph nodes and spleen, further confirming that the influence of PTPN22 on lymphopenia induced T cell proliferation was cell intrinsic and independent of the presence of other PTPN22 KO hematopoietic cells." (PMID 32047502, 2020). "We found that the absence of PTPN22 did not alter LCMV Cl13-induced lymphopenia (data not shown)." (PMID 28747914, 2017).
squamous cell carcinoma (4 papers, 2017 to 2025). A carcinoma arising from squamous epithelial cells. "Recently, epigenetic regulation of PTPN22 in the esophegal squamous cell carcinoma has been reported.We observed distinct hypomethylation of the PTPN22 promoter in OSCC, which also had inverse correlation with expression pattern of the gene." (PMID 28174608, 2017).
AIDS (3 papers, 2014 to 2020). A syndrome resulting from the acquired deficiency of cellular immunity caused by the human immunodeficiency virus (HIV). "The PTPN22 locus is one of the strongest risk factors outside of the MHC that associates with AIDs." (PMID 25289035, 2014).
asthma (3 papers, 2014 to 2025). "Additionally, polymorphisms in the PTPN22 (protein tyrosine phosphatase non-receptor 22) and CTLA-4 (cytotoxic T lymphocyte-associated antigen 4) genes have been strongly associated with asthma prevalence and morbidity." (PMID 40599789, 2025).
autoimmune hepatitis (3 papers, 2016 to 2022). Hepatitis caused by autoantibodies. "A Japanese study identified nine SNPs in the PTPN22 gene and found minor alleles at rs1217412, rs1217388, rs1217407, and rs2488458 less frequent in autoimmune hepatitis patients compared with controls." (PMID 36013501, 2022). "A Japanese population base study indicated that PTPN22 SNPs play an important role in the genetic resistance to autoimmune liver disease." (PMID 28977835, 2017). "This is in contrast with a genome-wide association study where PTPN22 was not related to autoimmune hepatitis patients of European descent." (PMID 36013501, 2022). "SNPs in the PTPN22 gene may therefore play key roles in the genetic resistance to autoimmune liver disease in the Japanese." (PMID 27406031, 2016).
coronary artery disease (3 papers, 2017 to 2024). "Interestingly, a significant association between PTPN22 expression and ischemic heart disease (IHD) was observed in patients with RA, after and adjustment for sex, age at time of study, and CV risk factors (p = 0.009)." (PMID 28874816, 2017). "Interestingly, a reduced PTPN22 expression was disclosed in RA patients with ischemic heart disease (p = 0.009)." (PMID 28874816, 2017).
lymphoma (3 papers, 2019 to 2023). A malignant (clonal) proliferation of B- lymphocytes or T- lymphocytes which involves the lymph nodes, bone marrow and/or extranodal sites. "To determine the longevity of effector CTLs following tumor clearance in vivo, we cotransferred control and PTPN22-deficient cells to transgenic C57BL/6-Ubc-GFP recipient mice bearing high-affinity EL4-OVA s.c. lymphomas." (PMID 31335326, 2019). "In line with the phenotype of Ptpn22-/- mice, adoptive transfer of Ptpn22-deficient OT-I T cells was shown to control the growth of OVA peptide-expressing lymphoma and ovarian carcinoma tumors more effectively and also enhance the efficacy of a TGFβ blocking antibody." (PMID 38022587, 2023).
periodontitis (3 papers, 2020 to 2025). An acute or chronic inflammatory process that affects the tissues that surround and support the teeth. "Although some studies have found an association of PTPN22 to inflammatory diseases, there have been no trials on severe periodontitis to date." (PMID 33059697, 2020). "Investigate the genetic variations of PTPN22, PADI4, and CTLA4 and their impacts on RA and periodontitis." (PMID 39811802, 2025).
Splenomegaly (3 papers, 2014 to 2024). Abnormal increased size of the spleen. "PTPN22-deficient mice developed age-dependent splenomegaly due to hyperactivation of lymphocytes, and knockdown of PTPN22 in human T cells with small interfering RNA (siRNA) led to enhanced TCR-mediated nuclear factor-kappa B (NF-κB) activity." (PMID 24433447, 2014). "Thus, PTPN22 R619W mice develop splenomegaly, associated with accumulation of activated effector T cell populations, increased germinal center formation and elevated serum Ig levels, similar to PTPN22-deficient mice." (PMID 39039893, 2024). "The association with the PTPN22 rs2488457 G/C polymorphism remained significant in the stratifications by age at onset, ANA status, splenomegaly, lymphadenectasis and involvement joints." (PMID 25781893, 2015). "The association with the PTPN22 rs2488457 G/C polymorphism was strong in JIA cases with an older age at onset and in those with ANA-positive status, splenomegaly, lymphadenectasis or more involvement joints." (PMID 25781893, 2015). "In terms of PTPN22 rs2488457 SNP, there were more cases with ANA-positive status, splenomegaly, lymphadenectasis or involvement joints in GC/CC versus GG." (PMID 25781893, 2015).
tuberculosis (3 papers, 2020 to 2025). A chronic, recurrent infection caused by the bacterium Mycobacterium tuberculosis. "Herein, we discussed the relevance of PTPN22-C1858T polymorphism and increased risk of tuberculosis and leprosy in humans." (PMID 33717071, 2021). "Detrimental effect of PTPN22-C1858T polymorphism-induced immune dysregulation on delayed-type hypersensitivity of tuberculosis and leprosy has been extensively studied." (PMID 33717071, 2021). "Hence, we conducted this meta-analysis to determine and articulate the relevance between PTPN22-C1858T polymorphism and risk of tuberculosis and leprosy." (PMID 33717071, 2021). "In addition to disease-causing microorganisms in the common disease spectrum, the susceptibility of individuals carrying PTPN22-C1858T SNP to tuberculosis and leprosy has been proposed in preceding studies." (PMID 33717071, 2021). "Moreover, other PTPN22 SNPs such as rs33996649 (PTPN22-G788A) might be related to raised susceptibility to tuberculosis." (PMID 33717071, 2021). "No publication bias on relavance between PTPN22-C1858T polymorphism and possibility to tuberculosis (P = 0.734) or leprosy (P = 1.000) was reflected in Begg’s funnel plot." (PMID 33717071, 2021). "In all genetic models, without indicated association between PTPN22-C1858T polymorphism and tuberculosis’s susceptibility." (PMID 33717071, 2021). "One of them was related to other SNPs in PTPN22, one was not related to tuberculosis or lepriasis, and two were not case-control studies." (PMID 33717071, 2021).
antiphospholipid syndrome (2 papers, 2013 to 2014). A disorder caused by the presence of autoantibodies directed against phospholipids, causing a hypercoaguable state, which may result in blood clots, stroke, heart attack, and in women, significant pregnancy-related complications, including miscarriage and still birth. "Significant association of the PTPN22 T1858 allele (CT + TT vs.CC) and secondary antiphospholipid syndrome was observed (p = 0.049)." (PMID 24985973, 2014). "Additionally, since rs2476601 was associated with aCL IgG our data suggests that this PTPN22 variant might be associated with pathogenesis of antiphospholipid syndrome in Europeans." (PMID 23950893, 2013). "In conclusion, this study shows that the carriage of PTPN22 T1858 allele predisposes to SLE, and it is associated with an increased risk of occurrence of antiphospholipid antibodies and secondary antiphospholipid syndrome." (PMID 24985973, 2014).
atopic dermatitis (2 papers, 2011 to 2024). "This study identified 18 genetic variants in PTPN22 that might be associated with atopic dermatitis in West Highland white terriers." (PMID 22208456, 2011).
Churg–Strauss syndrome (2 papers, 2020 to 2022). "The PTPN22 polymorphism is positively associated with microscopic polyangiitis (MPA) and granulomatosis with polyangiitis (GPA), formerly known as Wegener’s granulomatosis, but has not been reported in eosinophilic granulomatosis with polyangiitis (eGPA), formerly known as Churg–Strauss syndrome." (PMID 36013501, 2022).
Cirrhosis (2 papers, 2016 to 2022). A chronic disorder of the liver in which liver tissue becomes scarred and is partially replaced by regenerative nodules and fibrotic tissue resulting in loss of liver function. "However, no SNP or haplotype in the PTPN22 gene was associated with either cirrhosis in AIH or a history of orthotopic transplantation and disease progression of PBC (data not shown)." (PMID 27406031, 2016).
colon carcinoma (2 papers, 2024). "In this regard, the growth of transplanted MC38 colon carcinoma tumours is suppressed in PTPN22-deficient mice compared to control animals, particularly in the context of PD-1 immune checkpoint blockade." (PMID 38334623, 2024). "Thus CD8+ T cell responses to MC38 colon carcinoma tumors are elevated in Ptpn22-/- mice as compared to controls, while PTPN22-deficiency combined with PD-1 checkpoint blockade effectively cleared tumors." (PMID 39039893, 2024). "Ho and colleagues reported that treatment with a PTPN22 selective inhibitor, L-1, reduces the growth of MC38 and CT26 colon carcinomas in wild-type but not PTPN22-deficient mice." (PMID 38334623, 2024).
esophageal cancer (2 papers, 2016 to 2020). A primary or metastatic malignant neoplasm involving the esophagus. "To assess the clinical significance of PTPN22 methylation, we examined the association between PTPN22 methylation changes and the clinicopathological characteristics of esophageal cancer." (PMID 27613842, 2016). "Combined with the hypermethylation in tumor tissue, the current results suggest that aberrant PTPN22 methylation may suppress the expression of PTPN22 mRNA in esophageal cancer." (PMID 27613842, 2016). "CCLE analyses showed that in esophagus cancer cell lines, PTPN1, PTPN4 and PTPN12 were highly expressed; in gastric cancer cell lines, PTPN2 and PTPN12 were highly expressed; in colorectal cancer cell lines, PTPN12 was highly expressed while PTPN22 was downregulated." (PMID 32536826, 2020).
experimental autoimmune encephalomyelitis (2 papers, 2016 to 2022). An autoimmune demyelinating disease of the central nervous system that is produced experimentally in animals by the injection of homogenized brain or spinal cord in Freund's adjuvant. "Peripheral tolerance is maintained in vivo by keeping an appropriate balance between self-reactive T cells and Tregs, and Ptpn22 deficiency has been shown to be protective in NOD and experimental autoimmune encephalomyelitis mice model of disease due to increased Treg numbers." (PMID 27288531, 2016).
goiter (2 papers, 2020 to 2024). Enlargement of the thyroid gland usually caused by lack of iodine in the diet, hyperthyroidism, or thyroid nodules. "Younger age <40 yrs, higher serum fT4 level >40 pmol/l, higher serum TBII titre, larger goiter size at diagnosis, and genetic factors including PTPN22 C/T polymorphisms, and HLA subtypes DQB1*02, DQA1*05, and DRB1*03 were independent risk predictors for recurrence." (PMID 32477269, 2020).
granulomatosis with polyangiitis (2 papers, 2009 to 2022). A small-vessel necrotizing vasculitis characterized by the association of inflammation of the vessel wall and peri- and extravascular granulomatosis. "There is a prior study reporting an association between PTPN22 rs2476601 and Wegener's granulomatosis." (PMID 19951419, 2009).
juvenile dermatomyositis (2 papers, 2021 to 2022). Juvenile dermatomyositis (JDM) is the early-onset form of dermatomyositis (DM), a systemic, autoimmune inflammatory muscle disorder, characterized by proximal muscle weakness, evocative skin lesion, and systemic manifestations. "Increased CD4+ cells, TH-17, IL-6, an expanded B cell population, and the emerging role of natural killer cells, as well as the PTPN22 R620W variant, are all linked to the increased risk of developing juvenile dermatomyositis." (PMID 34354904, 2021).
ovarian carcinoma (2 papers, 2019 to 2023). A malignant neoplasm originating from the surface ovarian epithelium. "In the present work, we showed that Ptpn22–/– effector OT-1 CTLs had remarkable ability to target and kill ID8 ovarian carcinomas cells expressing the very low-affinity V4 OVA variant both in vitro and in vivo." (PMID 31335326, 2019).
polyarthritis (2 papers, 2015 to 2020). "Previous candidate gene association studies have shown that polyarthritis RF-positive JIA is associated with adult RA-associated loci, i.e., rs10499194 (TNFAIP3), rs2476601 (PTPN22), and rs7574865 (STAT4)." (PMID 33076506, 2020).
prostate tumors (2 papers, 2013 to 2026). "Genes overexpressed in NPp53T prostate tumors included Bglap3 and Ptpn22, which we previously identified as overexpressed in tumor cells upon Trim28 deletion, and granzyme E (Gzme), expressed in cytotoxic T cells." (PMID 41508128, 2026). "We further confirmed increased PTPN22 protein expression in NPp53T mouse prostate tumors compared to NPp53 tumors by immunostaining." (PMID 41508128, 2026). "We previously also reported increased gene expression of Ptpn22 in prostate tumor epithelial cells after Trim28 deletion, although Ptpn22 expression is not altered after Trim28 deletion in embryonic stem cells, neuronal progenitor cells, or adult liver." (PMID 41508128, 2026). "This analysis revealed a prominent inverse correlation between uc.106 + A expression and the expression of many interferon pathway genes such as IRF7, ISG15, ISG20, OAS1-3, and PTPN22 in prostate tumors." (PMID 23409773, 2013). "We also identified Ptpn22 as a gene repressed by TRIM28 in NPp53 prostate tumors, but not in ES cells, neural progenitor cells, or liver." (PMID 41508128, 2026).